P2RY13 (purinergic receptor P2Y13)
Description:
Receptor for ADP. Coupled to G(i)-proteins. May play a role in hematopoiesis and the immune system.
Synonyms: P2Y13; GPR86; GPR94; FKSG77; GPCR1; SP174
Tractability: Small molecule: a high-quality ligand is known; it belongs to a druggable protein family. Antibody: its Gene Ontology location is reachable by antibodies, with high confidence; UniProt places it where antibodies can reach, with medium confidence; UniProt predicts a signal peptide or a membrane-spanning region. PROTAC: a small molecule that binds it is known.
Target class: Family A G protein-coupled receptor; Membrane receptor
Gene: Protein-coding gene on chromosome 3 (151,326,312 to 151,329,549, reverse strand). Ensembl gene ENSG00000181631.
Subcellular location: Cell membrane
Pathways (Reactome):
Signal Transduction: G alpha (i) signalling events; P2Y receptors
Gene Ontology:
Molecular function: protein binding; G protein-coupled purinergic nucleotide receptor activity; G protein-coupled receptor activity
Biological process: G protein-coupled receptor signaling pathway; G protein-coupled purinergic nucleotide receptor signaling pathway
Cellular component: plasma membrane; endoplasmic reticulum; membrane
Genetic constraint (gnomAD): Loss-of-function variants: 0 observed, 2.54 expected, observed/expected ratio (o/e) 0, 90% interval 0 to 1.13. That is too few expected variants to judge how well the gene tolerates losing a copy. Missense variants: 387 observed, 419.83 expected, observed/expected ratio (o/e) 0.92, 90% interval 0.85 to 1. Synonymous variants: 146 observed, 155.93 expected, observed/expected ratio (o/e) 0.94, 90% interval 0.82 to 1.07.
Homologues: Orthologues: chimpanzee P2RY13 (95% identical), macaque P2RY13 (90% identical), rabbit P2RY13 (80% identical), guinea pig P2RY13 (78% identical), pig P2RY13 (76% identical), rat P2ry13 (75% identical), mouse P2ry13 (73% identical), tropical clawed frog p2ry13 (53% identical), zebrafish p2ry13 (43% identical). Paralogues in human: P2RY12 (43% identical), P2RY14 (40% identical), GPR87 (35% identical), GPR171 (28% identical), GPR34 (24% identical), PTAFR (21% identical).
Diseases named in the same sentence as P2RY13 in open-access papers:
P2RY13 is named in the same sentence as 49 diseases in open-access papers, as found by Europe PMC text mining. Sharing a sentence is not in itself a finding about the gene and the disease. The quoted sentences say what the papers report.
lung carcinoma (6 papers, 2020 to 2023). "P2RY13 is another member of a family of P2 purinergic receptor, which has been reported to be associated with the prognosis of lung cancer." (PMID 33318300, 2020). "After comparative analysis, we found that the expression of P2RY13 gene in different immune cells was different, especially in 13 lung cancer immune cells (P < 0.05)." (PMID 34494914, 2021). "And only purinergic receptors P2RX1, P2RX2, P2RX7, P2RY12, P2RY13, and P2RY14 were associated with good prognosis in the lung cancer." (PMID 32638267, 2020). "Although P2RY13 has been reported in lung cancer research, this study further investigated the role and possible mechanism of P2RY13 in lung adenocarcinoma from two aspects, namely, of the tumor microenvironment and immune cell infiltration." (PMID 33318300, 2020). "However, P2RX1, P2RX7, P2RY12, P2RY13, and P2RY14 were relatively downregulated in lung cancer tissues and were associated with a favourable prognosis." (PMID 33501930, 2021). "However, purinergic receptors P2RX1, P2RX7, P2RY12, P2RY13, and P2RY14 were relatively downregulated in lung cancer tissues and were associated with favorable prognosis." (PMID 32638267, 2020). "Interestingly, the immune process-related pathway was significantly enriched.To further clarify the correlation between P2RY13 gene expression and the occurrence or development of lung cancer, we verified it from two levels: RNA-seq in mouse models and IHC in human LUAD tissue." (PMID 34494914, 2021). "Based on the RNA-seq analysis of lung cancer tissue and normal tissue of tumor-bearing mice C57BL/6, we found that the expression of the P2RY13 gene in tumor tissues was significantly reduced (p < 0.001), and the difference was statistically significant." (PMID 34494914, 2021). "We also showed that contrast with the unfavorable prognosis of pyrimidine metabolic rate–limiting enzymes, purinergic receptors P2RX1, P2RX2, P2RX7, P2RY12, P2RY13, and P2RY14 were favorable prognostic markers in patients with lung cancer." (PMID 32638267, 2020). "created a novel Lung cancer prediction model that integrates 5 PyMGs, including P2RX1, P2RX7, P2RY12, P2RY13, and P2RY14, which might be utilized to predict prognosis in Lung cancerpatients." (PMID 37664033, 2023).
atherosclerosis (5 papers, 2013 to 2025). A disease characterized by the build-up of fatty material and calcium deposition in the arterial wall resulting in partial or complete occlusion of the arterial lumen. "MMP9, DAPK1, and P2RY13 tracked by flourishing AI nomogram (LASSO, RF, and SVM) were negatively related with Macrophages M1, translating as PCOS-mediated hub genes in atherosclerosis, with the latent pathogenesis lies in inflammatory response and immunity." (PMID 40549330, 2025). "We identified three candidate biomarkers for T2DM-related atherosclerosis—IL1B, MMP9, and P2RY13." (PMID 41516018, 2025). "Small-molecule agonists and antagonists of P2RY13 remain at the preclinical stage, so our data primarily support P2RY13 as an exploratory drug target and mechanistic link between metabolic dysregulation and plaque biology in T2DM-related atherosclerosis." (PMID 41516018, 2025).
lung adenocarcinoma (5 papers, 2020 to 2026). A carcinoma that arises from the lung and is characterized by the presence of malignant glandular epithelial cells. "Although P2RY13 has been implicated in immune regulation and prognosis in lung adenocarcinoma (LUAD), its specific cellular expression and functional mechanisms within the tumor microenvironment (TME) remain poorly understood." (PMID 41601785, 2026). "P2RY13 encodes a protein belongs to the family of G-protein coupled receptors, moreover, its high expression demonstrated significantly higher overall survival rates in patients with breast cancer and lung adenocarcinoma." (PMID 33597971, 2021).
breast carcinoma (4 papers, 2020 to 2023). "P2RY13 is a G-protein-coupled receptor, and it was reported to be decreased upon epidermal growth factor (EGF)- and hypoxia-induced epithelial–mesenchymal transition (EMT) in breast cancer cells." (PMID 35140706, 2021). "Overall, CCL19, CCL21, GPR183, P2RY13, and PENK were potential protective factors in breast cancer." (PMID 32195260, 2020).
acute myeloid leukemia (2 papers, 2021). Acute myeloid leukemia (AML) is a group of neoplasms arising from precursor cells committed to the myeloid cell-line differentiation. "However, previous studies reported that P2RY13 expression in acute myeloid leukemia was increased, and regulated cyclic adenosine monophosphate-mediated cytarabine resistance." (PMID 33996281, 2021).
Alzheimer disease (2 papers, 2023 to 2025). A progressive, neurodegenerative disease characterized by loss of function and death of nerve cells in several areas of the brain leading to loss of cognitive function such as memory and language. "Furthermore, it has been shown that P2RY13 is a purinergic receptor gene that regulates microglia homeostasis and is involved in Alzheimer's disease susceptibility through inflammatory and neurotrophic mechanisms when activated by ADP in hepatocellular carcinoma cell lines." (PMID 38045624, 2023). "The two identified microglial aging genes, P2ry13 and Slc16a3, are also found to be down- and up-regulated, respectively, in the so-called disease-associated microglia (DAM) that are found in Alzheimer’s disease as well as other neurodegenerative disorders." (PMID 39828750, 2025).
colitis (2 papers, 2022 to 2025). Inflammation of the colon. "Spearman's correlation analysis showed that the expression of P2RY13 in colon tissue was positively correlated with the severity of colitis." (PMID 35982893, 2022). "To explore whether P2RY13 activated by ADP or ATP has an impact on colitis, we used MRS2211 to inhibit the activity of P2RY13 in the DSS-induced colitis." (PMID 35982893, 2022). "Furthermore, we found that MRS2211-induced inhibition of P2RY13 activity significantly alleviated dextran sulfate sodium (DSS)-induced colitis." (PMID 35982893, 2022). "Our data strongly implicate a role of P2RY13 activation in the development of colitis." (PMID 35982893, 2022). "To further verify our hypothesis that activation of P2RY13 may promote the development of colitis through the IL-6/STAT3 signaling pathway, we generated intestinal epithelial cells STAT3 conditional knockout (STAT3△IEC) mouse strain as described in the Materials and Methods." (PMID 35982893, 2022). "To further confirm that the promoting effect of P2RY13 on UC development, we next assessed the effect of P2RY13 pharmacological inhibition on the development of DSS-induced colitis." (PMID 35982893, 2022). "To investigate the influence of P2RY13 on the development of UC, we first chose to explore the role of P2RY13 in the mouse model of DSS induced colitis." (PMID 35982893, 2022).
Stroke (2 papers, 2024 to 2025). Sudden impairment of blood flow to a part of the brain due to occlusion or rupture of an artery to the brain. "Thus, it appears that the protectiveness of the novel locus near AADACL2 against stroke may be associated with its epistatic interaction with the P2RY13 gene." (PMID 38317187, 2024).
ulcerative colitis (2 papers, 2023 to 2025). An inflammatory bowel disease involving the mucosal surface of the large intestine and rectum. "In addition, P2RY13 is highly expressed in the inflamed intestinal tissue of ulcerative colitis patients." (PMID 37063877, 2023).
viral infection (2 papers, 2021 to 2022). "Animal experiments showed that P2RY13 could protect hosts from viral infections, indicating that P2RY13 may be associated with inflammatory and immune reactions." (PMID 33996281, 2021).
bipolar disorder (1 paper, 2021). A disorder of the brain that causes unusual shifts in mood, energy, activity levels and the ability to carry out day-to-day tasks. "HEXB mRNA was increased in bipolar disorder compared to schizophrenia (14%, p = 0.025) and P2RY13 mRNA was reduced in bipolar disorder compared to controls (37%, p = 0.003)." (PMID 34911938, 2021).
co-infection (1 paper, 2012). "The only ID with known function was P2RY13, which showed lower expression levels in the co-infection groups than in the mono-infected groups." (PMID 23028845, 2012).
glioma (1 paper, 2019). A benign or malignant brain and spinal cord tumor that arises from glial cells (astrocytes, oligodendrocytes, ependymal cells). "(b) The log-fold change expression of SGmic genes (P2ry13, P2ry12, Gpr34, Slc2a5, Siglec-H, Olfml3, Tmem119, Fcrls) in glioma-associated microglia isolated from RCAS tumors compared to microglia isolated from healthy control brains is shown." (PMID 30764877, 2019). "(c) Graph shows the log-fold change expression of SGmic genes (P2ry13, P2ry12, Gpr34, Slc2a5, Siglec-H, Olfml3, Tmem119, Fcrls) in glioma-associated microglia isolated from GL261 tumors as compared to microglia isolated from healthy control brains." (PMID 30764877, 2019). "(a) The log-fold change expression of SGmic genes (P2ry13, P2ry12, Gpr34, Slc2a5, Siglec-H, Olfml3, Tmem119, Fcrls) in glioma-associated microglia isolated from experimental RCAS tumors compared to microglia isolated from healthy control brains is shown." (PMID 30764877, 2019).
lymph node metastasis (1 paper, 2021). "In addition, the expression level of P2RY13 in patients with lymph node metastasis in TCGA dataset was significantly decreased." (PMID 33996281, 2021).
Obesity (1 paper, 2025). Accumulation of substantial excess body fat. "P2RY13 is highly expressed in spleen, lymph nodes and bone marrow, is structurally related to P2RY12 sharing a high affinity for ADP, and P2RY13-mediated signaling protects against metabolic dysfunctions associated with obesity." (PMID 39995666, 2025).
status epilepticus (1 paper, 2018). Status epilepticus is defined as a continuous seizure lasting more than 30 min, or two or more seizures without full recovery of consciousness between any of them. "Status epilepticus: Increased P2ry2, P2ry4, and P2ry6 and decreased P2ry1, P2ry12, P2ry13, and P2ry14 transcript levels; increased P2Y1, P2Y2, P2Y4, and P2Y6 and decreased P2Y12 protein levels." (PMID 29563872, 2018).
tumor (15 papers, 2015 to 2026). "The consistent downregulation of P2RY13 in tumor tissues and its strong association with unfavorable survival outcomes highlight its clinical relevance." (PMID 41601785, 2026). "This aligns with clinical data showing that high P2RY13 expression correlates with improved prognosis, likely due to more effective anti-tumor immunity." (PMID 41601785, 2026). "P2RY13 expression was positively correlated with the infiltration of dendritic cells (DCs) in various of tumor tissues as validated by the PanglaoDB scRNA-seq database." (PMID 34494914, 2021). "The expression of P2RY13 and related pathways were verified by RNA-seq and immunohistochemistry based on the Lewis tumor-bearing model of C57BL/6 mice." (PMID 34494914, 2021). "Tumor-associated macrophages (TAMs) further divided into monocyte-derived brain macrophages (Mo-TAMs) expressed monocyte markers (TGFBI, VCAN, LYZ, and CLEC12A) and cells termed as Mg-TAMs expressed microglial signature genes (TMEM119, P2RY12, and P2RY13)." (PMID 39451239, 2024). "In summary, increased P2RY13 expression is related to tumor growth and poor survival and may promote tumorigenesis through abnormal inflammatory and immunological responses in ccRCC." (PMID 38045624, 2023). "The expression of CCR2 and P2RY13 was reduced in tumor tissues (P < 0.05)." (PMID 34494914, 2021). "Also, the expression of CCR2 and P2RY13 in LUAD tumor and normal tissues was verified by the THPA database." (PMID 34494914, 2021). "To further clarify the mechanism underlying the functions of the four previously discovered key genes (CCR2, CCR4, P2RY12, and P2RY13) in the tumor microenvironment, we divided LUAD patients into high-expression groups and low-expression groups according to the four gene expression levels." (PMID 33318300, 2020). "Additionally, epigenetic mechanisms, including promoter DNA methylation of P2RY13 in tumor-infiltrating DCs, may contribute to its transcriptional silencing." (PMID 41601785, 2026). "Our findings that P2RY13 expression correlates with an immunostimulatory DCs phenotype and enhanced T cell activation align with this paradigm, suggesting that modulating P2RY13 signaling could be a viable strategy to reinvigorate the anti-tumor immune response." (PMID 41601785, 2026). "We further hypothesize that ATP could be released via the transporter Pannexin 1, which was also upregulated in tumor cells (Log2FC 1.00, p.adj 2.76 × 10−4) and in turn activating purinergic receptors, such as P2RY13, while further inhibiting sodium transporters, such as SCNN1 components." (PMID 39038934, 2024). "To further investigate the role of P2RY13 in LUAD, we stratified 500 tumor samples from the TCGA-LUAD cohort by P2RY13 expression levels and compared those patients with the highest (n = 200) and lowest (n = 200) P2RY13 expression." (PMID 41601785, 2026). "Protein-protein interaction (PPI) and Cox regression analysis were performed on the differentially expressed genes (DEGs) to identify four key tumor microenvironment (TME) -related genes (CCR2, CCR4, P2RY12, and P2RY13)." (PMID 33318300, 2020). "In addition, P2RY13 has been identified as a prognostic biomarker in LUAD, correlating with improved clinical outcomes and modulating the tumor microenvironment (TME)." (PMID 41601785, 2026). "In addition, numerous immune-associated pathways were enriched in patients with LUAD with high P2RY13 level, indicating that P2RY13 may produce a marked effect on LUAD through influencing the TME and tumor immunization." (PMID 33996281, 2021). "As confirmed in IHC analysis of P2RY13 in LUAD patients obtained from HPA dataset, P2RY13 was primarily expressed in the interstitial tissue of normal lung, but is notably absent in LUAD tumor tissues." (PMID 41601785, 2026).
cancer (10 papers, 2008 to 2026). A tumor composed of atypical neoplastic, often pleomorphic cells that invade other tissues. "First, we used the TIMER2.0 database for P2RY13 to show the expression distribution of P2RY13 in 33 cancers." (PMID 38045624, 2023). "Based on this, calculation methods such as TIMER, XCELL, MCPCOUNTER, CIBERSORT, CIBERSORT-ABS were used to further analyze the correlation between the P2RY13 gene and DCs infiltration in pan-carcinoma." (PMID 34494914, 2021). "While our study focused on LUAD, the role of purinergic signaling in immune regulation suggests that P2RY13 might have broader implications in cancer immunity." (PMID 41601785, 2026). "IHC revealed that P2RY13 was expressed at higher levels in ccRCC compared to para‐cancer tissues." (PMID 38045624, 2023).
adenocarcinoma (1 paper, 2023). A common cancer characterized by the presence of malignant glandular cells. "Significant upregulation of TNFAIP6 and TLR6 and downregulation of P2RY13 and CYP27A1 were observed in all three adenocarcinoma cell lines." (PMID 38204755, 2023).
immune disorders (1 paper, 2022). "P2RY13 is a G protein-coupled receptor (GPCRs), which are involved in the pathogenesis of inflammation and immune disorders." (PMID 35982893, 2022).
neurological disorders (1 paper, 2019). "Intriguingly, P2ry13 and Gpr34, mouse orthologs of genes we identified in our human microglial gene set, are known to show down-regulation in so-called DAM that are found in AD and other neurological disorders." (PMID 31214167, 2019).
P2RY13 also shares sentences with these, for which no sentence is quoted: infection (4 papers); myocardial infarction (4); bacterial infection (2); dyslipidemia (2); acute myocardial infarction (1); angina (1); cardiovascular disease (1); diabetes (1); epilepsy (1); hemangioma (1); hematologic malignancies (1); hepatocellular carcinoma (1); Insulin resistance (1); ischemic heart disease (1); ischemic stroke (1); leukemia (1); lymphoma (1); malaria (1); melanoma (1); osteosarcoma (1); ovarian carcinoma (1); pancreatic insulinoma (1); periodontitis (1); Primary immunodeficiency (1); renal clear cell carcinoma (1); schizophrenia (1); urothelial carcinoma (1); venous thromboembolism (1).